DANCR (differentiation antagonizing non-protein coding RNA)
Synonyms: ANCR; KIAA0114; SNHG13; AGU2; lncRNA-ANCR
Gene: Long non-coding RNA gene on chromosome 4 (52,712,325 to 52,723,623, forward strand). Ensembl gene ENSG00000226950.
Gene Ontology:
Biological process: RNA processing
Cellular component: nucleolus
Diseases named in the same sentence as DANCR in open-access papers:
DANCR is named in the same sentence as 82 diseases in open-access papers, as found by Europe PMC text mining. Sharing a sentence is not in itself a finding about the gene and the disease. The quoted sentences say what the papers report.
osteosarcoma (28 papers, 2018 to 2026). A usually aggressive malignant bone-forming mesenchymal neoplasm, predominantly affecting adolescents and young adults. "Previous functional studies on lncRNA provide evidence that DANCR is a tumor-associated lncRNA and up-regulated in numerous human cancers, including breast cancer, prostate cancer, gastric cancer, and osteosarcoma." (PMID 30910839, 2019). "DANCR can also function as a ceRNA in osteosarcoma by binding to miR-335-5p and miR-1972, which promote ROCK1-mediated proliferation and metastasis." (PMID 41602364, 2026). "In osteosarcoma cell lines, DANCR up-regulated the expression of kinase AXL by acting as a sponge of miR-33a, leading to cell proliferation, migration, and metastasis." (PMID 38968577, 2024). "There was DANCR up regulation in osteosarcoma tissues that was positively correlated with the grade of tumor." (PMID 36740668, 2023). "DANCR inhibition suppressed osteosarcoma cell growth and invasion while induced apoptosis via miR-216a-5p/SOX5 axis." (PMID 36740668, 2023). "Recently, several studies identified that DANCR was increased in osteosarcoma tissues and tumor cell lines." (PMID 35252166, 2022). "Another study in osteosarcoma cells has indicated that inhibition of DANCR leads to decrease in ROCK1-mediated proliferation and metastasis." (PMID 35590326, 2022). "High expression of DANCR was linked to tissue typing and TNM stage as well as metastasis in osteosarcoma patients." (PMID 35252166, 2022). "The lncRNA DANCR has been documented to function by decoying miR-335-5p and miR-1972 in osteosarcoma and to facilitate ROCK1-mediated proliferation and metastasis." (PMID 35755302, 2022). "From a functional aspect, DANCR promotes progression of osteosarcoma through induction of cancer stem cells properties." (PMID 35590326, 2022). "Up-regulation of DANCR in osteosarcoma cells has been shown to promote xenograft tumor growth and lung metastases." (PMID 35590326, 2022). "In the current narrative review article, we summarize the roles of DANCR in the carcinogenesis, with an especial emphasis on its role in the development of osteosarcoma and lung, liver, pancreatic and colorectal cancers." (PMID 35590326, 2022). "Up-regulation of DANCR has been shown to upsurge proliferation, migratory propensity, and invasiveness of osteosarcoma cells." (PMID 35590326, 2022). "Expression of DANCR has been constantly enhanced in osteosarcoma samples, and its up-regulation has been positively associated with size of tumors and their metastatic ability." (PMID 35590326, 2022). "DANCR promotes progressive osteosarcoma by functioning as a ceRNA and sponging miR-335-5p and miR-1972, regulating ROCK1 expression." (PMID 35096852, 2021). "In recent studies, DANCR was found to function as a ceRNA to promote osteosarcoma progression by sponging miR-33a-5p, miR-216a-5p, miR-149, miR-335-5p, and miR-1972." (PMID 34722539, 2021). "Recently studies suggested that lnc-DANCR facilitates tumor progression of glioma as well as osteosarcoma by sponging miR-33a-5p." (PMID 32505219, 2020). "DANCR is shown to be upregulated in gastric cancer, lung cancer, glioma, colorectal cancer, retinoblastoma, osteosarcoma, oesophageal cancer, breast cancer, prostate cancer, and hepatocellular carcinoma." (PMID 32123519, 2020). "DANCR was reported to modulate PI3K-Akt pathway in osteosarcoma, β-catenin pathway in hepatocellular carcinoma, miR-634-RAB1A signaling pathway in glioma, androgen-AR signaling pathway in prostate cancer." (PMID 32123519, 2020). "DANCR was found to promote cancer initiation and progression in various cancer types, including lung cancer and osteosarcoma." (PMID 32010478, 2020). "Together, the indication of this part confirmed that elevation of DANCR promoted tumorigenesis and lung metastasis of osteosarcoma in vivo." (PMID 29753317, 2018).
osteosarcoma (continued). "The expression of DANCR in collected 95 cases of osteosarcoma tissues and matched para-tumor tissues were determined by applying of quantitative real-time PCR (qRT-PCR) as normalizing to GAPDH." (PMID 29753317, 2018). "Even further, the expression level of DANCR in 4 osteosarcoma cell lines MG-63, U2OS, MNNG/HOS, 143B and a normal human osteoblastic cell line hFOB 1.19 were also measured by qRT-PCR." (PMID 29753317, 2018). "Cumulatively, DANCR is an important regulator of osteosarcoma progression." (PMID 35590326, 2022). "In conclusion, these studies indicated that DANCR could be utilized as a potential therapeutic target for the treatment of osteosarcoma." (PMID 34722539, 2021). "The overexpression of DANCR could increase osteosarcoma cell proliferation, migration, and invasion in vitro, as well as promote xenograft tumor growth and lung metastasis in vivo." (PMID 33123287, 2020). "For example, the SNHG1 lncRNA sequestered miR-302/372/373/520 and consequently activated TGFBR2 and RAB11A in invasive pituitary tumors, while DANCR acted as a decoy for miR-335-5p and miR-1972, thus promoting ROCK1-associated proliferation and metastasis in osteosarcomas." (PMID 30774556, 2019). "Since DANCR was highly expressed in osteosarcoma and was correlated with tumor size and distant metastasis in clinical cases, we wondered about the function DANCR might act on osteosarcoma cells’ proliferation and metastasis." (PMID 29753317, 2018). "And this lower expression level of miR-335-5p and miR-1972 indirectly provided the possibility that DANCR might co-work with them in the progression of osteosarcoma." (PMID 29753317, 2018). "Here, we attempted to figure out whether the regulation effect of DANCR on osteosarcoma cells’ proliferation and migration/invasion was achieved through ROCK1." (PMID 29753317, 2018). "DANCR can promote the pathogenesis of osteosarcoma, and the silencing of DANCR has been demonstrated to promote programmed cell death, using functional assays, to inhibit the replication, migratory ability, invasiveness, and autophagic capability of cells from osteosarcomas." (PMID 39015175, 2024). "Increased expression of DANCR could be detected in osteosarcoma tissues and cell lines." (PMID 34722539, 2021). "DANCR suppression could restrain osteosarcoma progression by inhibiting autophagy." (PMID 34722539, 2021). "Therefore, we specuated whether DANCR might crosstalk with any potential miRNAs in dependence of the same mechanism in osteosarcoma." (PMID 29753317, 2018). "Also, DANCR was intensively stained in osteosarcoma cells’ cytoplasm." (PMID 29753317, 2018). "miRNA-335-5p and miRNA-1972 expression are also promoted by DANCR, which accelerates replication that is induced via ROCK1 and ceRNA network transfer and consequently promotes the pathogenesis of osteosarcomas." (PMID 39015175, 2024). "When DANCR was knocked down, it lowered the EZH2 expression and activated both p21 and p27, hence inhibiting the osteosarcoma cell proliferation, migration, and invasion." (PMID 35755302, 2022). "Several studies found the interaction between DANCR and EZH2 in many tumor types including osteosarcoma." (PMID 35755302, 2022). "The interaction between DANCR and EZH2 was also found in osteosarcoma, which led to the inhibition of p21 and p27 expression." (PMID 34722539, 2021). "Later, DANCR was found to be important in supporting cancer cell stemness in hepatocellular carcinoma (HCC) and osteosarcoma." (PMID 31804607, 2020). "DANCR acts as a ceRNA to promote REOCK1 by acting as bait for miR-335-5p and miR-1972 in osteosarcoma." (PMID 32163372, 2020). "DANCR promotes ROCK1-mediated proliferation and metastasis via crosstalk with miR-335-5p and miR-1972 in osteosarcoma." (PMID 32019566, 2020).
osteosarcoma (continued). "In the present study, we focused on the ceRNA network which is comprising of DANCR, miR-335-5p/miR-1972 and ROCK1, as well as explored the potential effect of DANCR to ROCK1 - mediated proliferation and migration/invasion in osteosarcoma." (PMID 29753317, 2018). "Functional experiments illustrated that a depression of DANCR suppressed ROCK1-mediated proliferation and metastasis in osteosarcoma cells." (PMID 29753317, 2018). "DANCR competitively binds to miR-335-5p and miR-1972 to regulate the expression of ROCK1, thus promoting the malignant biological behaviours of osteosarcoma." (PMID 30419948, 2018). "Mechanistically, DANCR stimulated tumor malignant phenotype via enhancement of CSCs features, which might be due to activation of PI3K/Akt signaling pathway in osteosarcoma." (PMID 35252166, 2022). "Moreover, DANCR inhibited migration and invasion via targeting miR-149 and its downstream MSI2 in osteosarcoma." (PMID 35252166, 2022). "In addition, DANCR acted as a ceRNA to sponge miR-335-5p and miR-1972, leading to inhibition of ROCK1 expression and depression of proliferation and motility of osteosarcoma cells." (PMID 35252166, 2022). "For example, DANCR is able to upregulate CTNNB1 in HCC, and activate AKT pathway in osteosarcoma." (PMID 31804607, 2020). "Moreover, METTL3 promotes osteosarcoma progression by increasing the stability of DANCR mRNA through m6A modification, which means that METTL3 may be a promising therapeutic target for osteosarcoma treatment." (PMID 39015175, 2024).
glioma (27 papers, 2018 to 2024). A benign or malignant brain and spinal cord tumor that arises from glial cells (astrocytes, oligodendrocytes, ependymal cells). "High DANCR expression is associated with increased malignancy and an unfavourable prognosis in glioma patients." (PMID 38877534, 2024). "All these results suggested that high expression of DANCR was associated with glioma progression, and promoted us to explore its biological function more deeply." (PMID 32099526, 2020). "In the present study, we found that DANCR expression was markedly increased and positively associated with advanced tumor grade in glioma patients." (PMID 29301870, 2018). "Interestingly, DANCR was found to activate the NF-κB signaling and cause cisplatin resistance in glioma cells." (PMID 38968577, 2024). "In fact, except for increasing Ara‐C resistance in AML cells, DANCR has also been shown to mediate cisplatin resistance in glioma cells, implying that DANCR may be implicated in the regulation of chemoresistance in other scenarios." (PMID 33638615, 2021). "Additionally, we determined the expression of RAB1A in glioma tissue samples by qRT-PCR, results showed that RAB1A expression was significantly increased and positively associated with DANCR expression in glioma tissues (P<0.05)." (PMID 29301870, 2018). "Furthermore, we found that high DANCR expression levels were positively associated with advanced tumor grade (III-IV) of glioma (P<0.05)." (PMID 29301870, 2018). "Furthermore, we found RAB1A was up-regulated in glioma tissue samples and positively associated with the expression of DANCR." (PMID 29301870, 2018). "Moreover, DANCR has been reported to be strongly associated with glioma malignancy." (PMID 38229597, 2024). "However, the role and underlying molecular mechanisms of DANCR in cisplatin resistance in glioma cells remain unclear." (PMID 34065991, 2021). "However, the expression and the underlying roles of DANCR in glioma are still unclear." (PMID 29301870, 2018). "Suppression of DANCR has been shown to impede glioma cell proliferation, migration, invasion, and angiogenesis." (PMID 38877534, 2024). "In glioma cells, DANCR is positively correlated with autophagy, enhancing malignant progression by upregulating ATG7 protein expression and promoting autophagy-mediated malignant transformation." (PMID 38877534, 2024). "DANCR is significantly upregulated in glioma tissues and cell lines, and its elevated expression is correlated with an advanced tumour grade." (PMID 38877534, 2024). "In glioma cells, DANCR was shown to act as ceRNA to miR-634, a miRNA shown to increase glioma cell sensitivity to temozolomide." (PMID 36497269, 2022). "Based on the documented roles of DANCR and IGF2BP2 in glioma and their correlation in certain cancers, we aimed in this study to explore the interaction between DANCR and IGF2BP2 in drug resistance in GBM cells." (PMID 35141227, 2021). "We then confirmed the upregulated expression of DANCR both in glioma tissues and various GBM cells (U251MG, LN229, LN18, and T98G)." (PMID 35141227, 2021). "IGF2BP2 and DANCR were highly expressed in glioma cells and tissues, whereas PID1 and FOXO1 were poorly expressed." (PMID 35141227, 2021). "DANCR, an important cancer-related lncRNA, is known to promote cell growth in glioma and induce drug resistance through certain signaling pathways or sponging microRNAs." (PMID 35141227, 2021). "Based on these results, DANCR promotes cisplatin resistance by activating the AXL/PI3K/Akt/NF-κB signaling pathway in gliomas." (PMID 34065991, 2021). "Conversely, the lncRNA DANCR promotes cisplatin resistance by activating the AXL/PI3K/Akt/nuclear factor κB signaling pathway in glioma." (PMID 35141227, 2021). "By upregulating AXL, DANCR activated the PI3K/Akt/NF-κB signaling pathway in glioma cells, and inhibition of this signaling pathway reversed the effect of DANCR on cisplatin resistance." (PMID 34065991, 2021).
glioma (continued). "DANCR, which is upregulated in glioma, that activates the Wnt/β-catenin signaling pathway, leading to increased migration and proliferation of glioma cells." (PMID 33980320, 2021). "A previous study found that DANCR activates Wnt/β-catenin signaling to promote glioma proliferation." (PMID 31986122, 2020). "Inhibition of DANCR suppressed the glioma cell proliferation and induced cell arrested in the G0/G1 phase." (PMID 33123287, 2020). "DANCR contained a binding site of miR-33a-5p and DANCR expression was negatively correlated with the expression of miR-33a-5p in glioma tissues." (PMID 33123287, 2020). "A previous study found that DANCR activated Wnt/β-catenin signaling to promote glioma proliferation." (PMID 31986122, 2020). "DANCR promotes tumor progression and angiogenesis in glioma and stimulates glioma proliferation by activating the WNT/β-catenin pathway." (PMID 31986122, 2020). "Although recent studies showed DANCR regulation of Wnt/β-catenin signaling in glioma and osteoblasts, this is the first report to establish this interaction in lung cancer cells, and the interplay of DANCR, miR-216a, and Wnt/β-catenin signaling." (PMID 33302540, 2020). "DANCR has previously been reported to activate the Wnt/β-catenin signaling pathway in hepatocellular carcinoma, gastric cancer, and glioma." (PMID 32123519, 2020). "Altogether, these data indicated that DANCR played an essential role in glioma cell proliferation, migration and invasion." (PMID 32099526, 2020). "DANCR knockdown inhibited cell proliferation, migration and invasion in glioma cells through regulating miR-135a-5p/BMI1 axis, providing viable therapeutic avenues for treatment of glioma." (PMID 32099526, 2020). "A xenograft tumor model was established to investigate the functions of DANCR in glioma progression in vivo." (PMID 32099526, 2020). "DANCR expression was positively correlated with the malignancy and poor prognosis of glioma patients." (PMID 33123287, 2020). "DANCR was known to mediate cisplatin resistance in glioma cells via activating AXL/PI3K/Akt/NF-κB signaling pathway." (PMID 32766131, 2020). "In our study, we found that the abundance of DANCR was also increased in glioma tissues and cells, and patients with high DANCR expression had poor survival compared with low DANCR expression, which is consistent with previous reports." (PMID 32099526, 2020). "Our results showed that DANCR was significantly up-regulated in glioma tissues and cell lines (U251, U118, LN229, and U87MG)." (PMID 29301870, 2018). "In the present study, we determined the expression of DANCR in glioma tissues and cell lines using qRT-PCR and further defined the biological functions." (PMID 29301870, 2018). "Down-regulated expression of DANCR inhibited glioma cells growth and arrested cell cycle in G0/G1 phase." (PMID 29301870, 2018). "Taken together, these findings suggested that miR-634 in glioma cells was regulated by lncRNA DANCR." (PMID 29301870, 2018). "Results showed that DANCR expression was significantly up-regulated in glioma cell lines (U251, U118, LN229, and U87MG) compared with that in normal human astrocytes (NHA) cells (P<0.05)." (PMID 29301870, 2018). "CCK-8 assay showed that miR-634 inhibitors attenuated the suppressing proliferation effect of DANCR knockdown in glioma cells (P<0.05), which was also observed in colony formation assay (P<0.05)." (PMID 29301870, 2018). "In the present study, our data showed that DANCR inhibition suppressed RAB1A expression in glioma cells, and miR-634 inhibitors restored the reduction of RAB1A expression in DANCR suppressed glioma cells." (PMID 29301870, 2018). "To identify the role of DANCR in glioma progression, we analyzed the expression of DANCR in 47 glioma tissue samples and 14 normal brain (NB) tissue samples using qRT-PCR." (PMID 29301870, 2018).